ALB (albumin)
Diseases named in the same sentence as ALB in open-access papers (continued):
Sharing a sentence is not in itself a finding about the gene and the disease.
atherosclerosis (152 papers, 2006 to 2026). A disease characterized by the build-up of fatty material and calcium deposition in the arterial wall resulting in partial or complete occlusion of the arterial lumen. "Albumin possesses antioxidant properties that can mitigate cell damage caused by free radicals, thereby potentially inhibiting the progression of atherosclerosis." (PMID 40099259, 2025). "Other researchers have found that worse coronary flow reserve was associated with higher UACR, and higher urinary albumin excretion, even within the normal range, is associated with early atherosclerosis in type 1 diabetes during mid-adolescence." (PMID 40574952, 2025). "Additional regression analysis revealed that H. pylori, age, BMI, albumin, and total cholesterol were independent risk factors for the cholesterol crystals and atherosclerosis." (PMID 40125519, 2025). "The glycosylation of albumin causes the impairment of the antioxidant activity of albumin, thereby accelerating the process of atherosclerosis." (PMID 39264001, 2024). "So a lower level of plasma albumin is related to the higher risk of atherosclerosis and poor prognosis, which further support the potential role of albumin for CSFP." (PMID 39003493, 2024). "Recent studies have found that serum albumin levels are associated with atherosclerosis, with lower albumin levels exacerbating atherosclerosis and increasing the risk of hospitalization and death, independent of pre-existing disease." (PMID 37210474, 2023). "Inflammation plays an important role in all stages of atherosclerosis, meaning that a decreased albumin level and increased CRP level are associated with the chronic nature of the disease." (PMID 37762611, 2023). "An inverse relationship was found between the level of oxidised albumin and the risk of atherosclerosis." (PMID 33050223, 2020). "SARS-CoV-2 interactome strongly connects with the complete ACE2 network through INS, CDK4 (Cyclin-Dependent Kinase 4), CCL2, and ALB (Albumin), all of them associated with atherosclerosis processes." (PMID 33233425, 2020). "Low serum albumin is usually associated with cardiovascular risk factors and accelerated atherosclerosis." (PMID 31737067, 2019). "Low serum albumin was associated with a significant increase of cIMT, a measure of subclinical atherosclerosis that predicts future CVD outcomes in the general population." (PMID 30515432, 2018). "The passage of albumin and other macromolecules into the vessel wall causes inflammation, lipid accumulation, and eventual atherosclerosis." (PMID 25742159, 2015). "Many factors that have a close association with the urinary excretion of albumin in the present study also promote atherosclerosis." (PMID 23830507, 2013). "Furthermore, a decrease in serum albumin indicates potential inflammation, which causes the progression of atherosclerosis." (PMID 39339776, 2024). "Additionally, the oxidative modifications of albumin, such as carbonylation, have been implicated in the inflammatory processes associated with atherosclerosis." (PMID 38396639, 2024). "In addition, albumin also has significant anticoagulant properties, which helps prevent changes in cardiac structure and electrophysiology caused by atherosclerosis, thus maintaining the stability of circulating blood flow and normal function of the heart." (PMID 38655495, 2024). "In addition, decreased serum albumin indicates underlying inflammation, which provokes the progress of atherosclerosis." (PMID 36966329, 2023). "In addition, as a chronic inflammatory disease, atherosclerosis correlates with increased production of catabolic cytokines, muscle catabolism, and appetite suppression, thus causing a decline in albumin levels." (PMID 36286310, 2022). "Oxidative stress and inflammation play pivotal roles in the development and progression of atherosclerosis, which affects circulatory proteins, including albumin and fibrinogen, thereby causing an imbalance in albumin to globulin and fibrinogen to albumin ratios." (PMID 35881574, 2022).
atherosclerosis (continued). "Our magnetic resonance imaging (MRI) study investigates the feasibility of using two different molecular MRI probes for the simultaneous assessment of ECM-associated intraplaque albumin deposits caused by endothelial damage and progressive inflammation in atherosclerosis." (PMID 34681063, 2021). "Besides this, glycated albumin reflects the risk of subclinical atherosclerosis assessed by the carotid intima-media thickness in middle-aged and elderly Chinese populations with impaired glucose regulation." (PMID 34684632, 2021). "A single in vivo molecular MRI session implementing a dual-probe application was shown to be a feasible method to assess vessel wall dysfunction by detecting matrix-associated albumin deposits, as well as plaque burden and inflammatory processes in mice suffering from progressive atherosclerosis." (PMID 34681063, 2021). "Additionally, albumin can bind to homocysteine to lower the serum levels of homocysteine, which is a risk factor for atherosclerosis." (PMID 34869630, 2021). "Materials and Methods: Data of 164 community individuals were analyzed, and demographic information, related disease history, atherosclerosis risk factors, certain laboratory tests, the estimated eGFR, and urine albumin creatinine ratio (UACR) were recorded for each individual." (PMID 31569560, 2019). "In analyses where IMT was the marker of atherosclerosis, histidine, N,N-dimethylglycine, and albumin showed strong inverse associations below the MWSL threshold (P = 7 × 10−7 to 6.7 × 10−6); 14 other metabolites retained nominal statistical significance (P < 0.05)." (PMID 31102408, 2019). "On the other hand, its inverse association with urinary excretion of albumin should be valued and may indicate a role for lower levels of vitamin D, even though currently classified as "normal", at an earlier stage of atherosclerosis in this population." (PMID 29490002, 2018). "Serum albumin is able to bind to many ligands including copper and iron, long-chain fatty acids, bilirubin, and homocysteine, preventing them from contributing to oxidized reactions, which are known risk factors for atherosclerosis." (PMID 30515432, 2018). "While a causal relationship between plasma lipids and BBB cannot be assumed, the most plausible explanation may be that BBB integrity in AD detected by the CSF Albumin Index is related to atherosclerosis and its risk factors." (PMID 22654903, 2012). "Another study showed that serum albumin is able to bind to a number of ligands, including bilirubin, long-chain fatty acids, homocysteine, copper and iron, preventing them from causing the oxidative reactions that are already involved in atherosclerosis known risk factors." (PMID 37210474, 2023). "In terms of the pathological mechanism of the relationship between urine albumin-creatinine ratio and all-cause death, proteinuria may be an early sign of vascular endothelial dysfunction, which easily leads to the development of individual atherosclerosis." (PMID 34983421, 2022). "Serum albumin may be a marker of susceptibility to atherosclerosis." (PMID 27548057, 2016). "The transference of albumin to the arterial wall leads to lipid accumulation, inflammation, and the development of atherosclerosis." (PMID 40224627, 2025). "Consistent with these latter studies, we presently observed that patients with T2D exhibited elevated features of clinical atherosclerosis characterized by an increase in S1P bound to albumin." (PMID 39984928, 2025). "An important role in the pathogenesis of atherosclerosis is played by the genes ALB, SHBG, APOC, APOC3, APOC4, and SAA4, of which APOC3 and APOC4 make a major contribution to the occurrence of atherosclerosis and also to insulin resistance and type 2 diabetes." (PMID 40361926, 2025). "Inflammation drives atherosclerosis growth, with cytokines like interleukin-1, interleukin-6, and tumor necrosis factor sparking the acute-phase reaction and curbing albumin synthesis." (PMID 41536368, 2025).
atherosclerosis (continued). "Albumin serves as an anti-inflammatory agent by specifically diminishing cytokine-triggered endothelial activation, which is pivotal in conditions such as atherosclerosis." (PMID 40279952, 2025). "It has been found that elevated urinary albumin excretion increases the prevalence of cardiovascular complications such as atherosclerosis in patients with RA." (PMID 39364405, 2024). "68Ga-labeled NOTA-neomannosylated human serum albumin has been investigated in atherosclerosis, myocarditis, and pulmonary artery hypertension in animal models." (PMID 37474271, 2023). "On the other hand, the inflammatory response that exists during the progression of atherosclerosis can inhibit the synthesis of albumin, resulting in a decrease in the level of albumin and further aggravation of atherosclerosis." (PMID 37210474, 2023). "A key role is played by a polysaccharide gel called glycocalyx, which acts as a barrier against albumin filtration, endothelial cell activation and glycocalyx degradation, leading to atherosclerosis, which lead to cardiovascular disease together." (PMID 37563647, 2023). "Low serum albumin was also reported as a powerful predictor of cardiovascular adverse events in healthy subjects and patients with subclinical atherosclerosis." (PMID 36558522, 2022). "Low albumin levels have been considered as a marker of persistent arterial damage and progression of atherosclerosis and thrombosis." (PMID 35252328, 2022). "ALB has anti-atherosclerotic properties, such as anti-inflammatory and antioxidant effects, as well as being a marker of nutritional status; therefore, individuals with relatively higher ALB would be protected against atherosclerosis." (PMID 34511560, 2021). "Recent studies have demonstrated that ALB takes an active role in the pathophysiology of thrombosis, coagulation, and atherosclerosis." (PMID 34733230, 2021). "We assessed plasma adiponectin and its correlation with carotid intima-media-thickness (CIMT), as a marker of atherosclerosis, and urine albumin/creatinine ratio (ACR) in patients with non-alcoholic fatty liver disease (NAFLD)." (PMID 33166436, 2021). "In our study, we assessed plasma adiponectin and its correlation with CIMT, as a marker of atherosclerosis, and urine albumin/creatinine ratio (ACR) in patients with NAFLD." (PMID 33166436, 2021). "With advancing atherosclerosis, albumin-based MRI signal enhancement and ferumoxytol-induced signal loss areas in T2*-weighted MRI increased." (PMID 34681063, 2021). "Among the differentially expressed proteins the inflammatory marker albumin, atherosclerosis marker apolipoprotein A-IV and hedgehog-interacting protein marker of angiogenesis were predominantly associated with the impaired LVEF <45 group." (PMID 35423047, 2020). "The Fässler group also used albumin-cre mice in later work, they analyzed the role of FN in many different pathophysiological states such as atherosclerosis, skeletal muscle regeneration and many others." (PMID 33194415, 2020). "Among the differentially expressed proteins the inflammatory marker albumin, atherosclerosis marker apolipoprotein A-IV and hedgehog-interacting protein marker of angiogenesis were predominantly associated with impaired LVEF <45 group." (PMID 35423047, 2020). "Advanced glycation end products, resulting from the early stage of protein glycation (such as HbA1c and glycol-albumin) by a series of oxidation, dehydration, and condensation reactions, was believed to involved in each step of atherosclerosis." (PMID 31727070, 2019). "Measures of serum albumin, carotid intima media thickness ([cIMT] surrogate marker of atherosclerosis), inflammation, T cells, monocyte activation, and gut integrity were assessed at baseline, 48 and 96 weeks later." (PMID 30515432, 2018). "Low serum albumin, in virally suppressed participants, also predict progression of subclinical atherosclerosis over time." (PMID 30515432, 2018).
atherosclerosis (continued). "It is known that both albumin and calcium as inflammatory factors impact on accelerated atherosclerosis and vascular calcification." (PMID 28642879, 2017). "Rosiglitazone, fenofibrate and the LXR-agonist T0901317 improved the albumin/creatinine ratio, but the same compounds tended to promote the development of atherosclerosis." (PMID 23457508, 2013). "We next analyzed hepatic triglyceride concentrations, albumin/creatinine ratio and atherosclerosis as measures of diabetic complications in liver, kidney and vessel wall." (PMID 23457508, 2013). "The passage of albumin and other macromolecules into the vessel wall culminates in an inflammatory response, lipid accumulation, and eventually atherosclerosis." (PMID 23805186, 2013). "Existing studies indicated that decreased albumin concentrations might serve as an indicator of sustained arterial injury and advancement of thrombosis as well as atherosclerosis." (PMID 40568584, 2025). "As the most abundant plasma protein component, albumin protects the vascular wall by playing an antioxidant role against oxidative damage to the vascular endothelium, therefore inhibiting the progression of atherosclerosis." (PMID 40102522, 2025). "Additionally, atherosclerosis represents a low-level inflammatory process, which leads to altered metabolism, muscle catabolism, and reduced serum albumin levels." (PMID 39882039, 2024). "Serum albumin levels are significantly negatively correlated with thiobarbituric acid-reactive substances and advanced protein oxidation products of atherosclerotic plaques, indicating that serum albumin has antioxidant effects and decreased serum albumin levels can promote atherosclerosis." (PMID 38751736, 2024). "While albumin itself is not directly implicated in the development of atherosclerosis, its levels and the presence of certain modifications to albumin can be relevant in assessing cardiovascular health." (PMID 38396639, 2024). "There is a correlation between serum albumin level and atherosclerosis." (PMID 37210474, 2023). "There is a correlation between the fraction of oxidized albumin and atherosclerosis development." (PMID 37926735, 2023). "Serum albumin is an acute phase protein whose serum levels are affected by the nutritional status, inflammatory responses, and fluid status, exerting a protective effect in atherosclerosis via its anti-inflammatory, anti-oxidant, and anti-thrombotic roles." (PMID 37316853, 2023). "It demonstrated that a low concentration of serum albumin in the blood is a prognostic factor of atherosclerosis in blood vessels, regardless of traditional risk factors and statin therapy in patients with HIV infection." (PMID 36361589, 2022). "The severity of atherosclerosis can be predicted by the fibrinogen to albumin ratio (FAR)." (PMID 35881574, 2022). "Second, serum albumin can effectively inhibit human endothelial cell apoptosis, and the integrity of the endothelial structure and function of arterial cells is an important condition for preventing atherosclerosis and preventing thrombosis." (PMID 36154556, 2022). "Serum albumin has antioxidant and anti-inflammatory activities and inhibits platelet aggregation, and anticoagulation activation, so lower serum albumin levels contribute to accelerated atherosclerosis in several ways." (PMID 36286310, 2022). "As for potential biomarkers for atherosclerosis, serum albumin is used as a target protein." (PMID 34681063, 2021). "Finally, the predictors of that study were microalbuminuria (30–300 μg albumin/mg creatinine) and subclinical atherosclerosis (defined as increased carotid intima-media thickness, decreased ankle-brachial index or increased left ventricular weight)." (PMID 34798829, 2021). "Lower albumin levels may be a marker of persistent injury to the arteries and the progression of atherosclerosis and thrombosis." (PMID 32370130, 2020).
atherosclerosis (continued). "This study suggests that increased urinary IgM may be a more specific marker of atherosclerosis (associates with ABI), whereas increased albumin excretion could be mediated or reflected by a wide variety of cardiovascular abnormalities." (PMID 32758145, 2020). "Urinary NAG may be a more sensitive biomarker than urinary albumin for early detection of atherosclerosis." (PMID 28122570, 2017). "As stated in almost all studies on DR, the condition is closely related to duration of the disease, higher blood pressure and a higher albumin excretion rate, all of which may contribute to the increased atherosclerosis in these patients." (PMID 25856787, 2015). "A greater capillary permeability for albumin in the systemic vasculature may lead to a generalized hemodynamic strain and disequilibrium, which ultimately initiates atherosclerosis." (PMID 24278288, 2013). "Alterations of the redox state of serum albumin with impaired scavenging activity could contribute to accelerated atherosclerosis and the development of cardiovascular disease in HD patients." (PMID 23923025, 2013). "Increased oxidative stress resulting from biological changes in serum albumin levels could contribute to accelerated atherosclerosis and the development of cardiovascular disease in HD patients." (PMID 23923025, 2013). "However, its relationship with subclinical atherosclerosis in diabetic patients with early-stage kidney injury, characterized by an elevated urinary albumin-to-creatinine ratio (ACR), remains unclear." (PMID 41859543, 2026). "Our results indicated that CHP functionalized albumin nanoparticles could provide real-time observation of atherosclerotic lesions and significantly enhance the therapeutic effect of paclitaxel in treating atherosclerosis." (PMID 41152999, 2025). "It posits that primary active ingredients of THL – quercetin, salidroside, and oleanolic acid – may exert effects on targets like ALB, EGFR, SRC, potentially modulating pathways associated with cancer, lipid and atherosclerosis, and IL-17 signaling in the context of PN intervention." (PMID 38905418, 2024). "Considering the pivotal role of oxidative stress in the pathogenesis of atherosclerosis and the well-known increased risk of CVD in patients suffering from rheumatic diseases, oxidative forms of human ALB could help clinicians earlier identify patients in whom a more stringent follow-up is needed." (PMID 37762957, 2023). "This may result in a vicious cycle that promotes atherosclerosis and decreases serum albumin." (PMID 36286310, 2022). "Furthermore, we found that urinary NAG might be a more sensitive urinary biomarker than urinary albumin for early detection of atherosclerosis." (PMID 28122570, 2017). "Previous studies have demonstrated that glycated albumin induces oxidative stress in the vessel wall, enhances pro-inflammatory endothelial response to S100A8/A9, and promotes proliferation and migration of vascular smooth muscle cells, and thereby is associated with accelerated atherosclerosis." (PMID 17178005, 2006). "Numerous studies have demonstrated that bilirubin, like albumin, acts as an antioxidant molecule that plays an important role in preventing the oxidation of LDL-C, a key factor in atherosclerosis." (PMID 40364067, 2025). "Consequently, CHP functionalized albumin nanoparticles could realize the targeted identification and treatment of atherosclerotic plaques, which was expected to provide a promising solution for the future atherosclerosis molecular imaging and treatment." (PMID 41152999, 2025). "Consistent with our expectations, ex vivo experiments on atherosclerosis have demonstrated that NOB can interfere with the atherosclerotic process by modulating core targets, such as ALB, AKT1, and CASP3." (PMID 38468335, 2024). "Neutrophil–lymphocyte ratio (NLR), C-reactive protein (CRP), and serum albumin (ALB) are established indicators of inflammation and atherosclerosis pathogenesis." (PMID 38982273, 2024).